RRH (retinal pigment epithelium-derived rhodopsin homolog)
Description:
Opsin-family protein localized to the apical microvilli of the retinal pigment epithelium (RPE), where it may participate in retinoid exchange between photoreceptors and RPE or light-dependent retinoid processing. Although it possesses the structural features of a GPCR, no evidence for canonical G protein activation in vivo has been reported.
Synonyms: peropsin
Tractability: Small molecule: it belongs to a druggable protein family. Antibody: its Gene Ontology location is reachable by antibodies, with high confidence; UniProt predicts a signal peptide or a membrane-spanning region.
Gene: Protein-coding gene on chromosome 4 (109,827,972 to 109,849,123, forward strand). Ensembl gene ENSG00000180245.
Subcellular location: Membrane; Apical cell membrane
Pathways (Reactome):
Signal Transduction: G alpha (i) signalling events; Opsins
Gene Ontology:
Molecular function: protein binding; G protein-coupled photoreceptor activity; G protein-coupled receptor activity
Biological process: cellular response to light stimulus; G protein-coupled receptor signaling pathway; phototransduction; visual perception; detection of visible light
Cellular component: plasma membrane; apical plasma membrane; membrane
Genetic constraint (gnomAD): Loss-of-function variants: 30 observed, 29.83 expected, observed/expected ratio (o/e) 1.01, 90% interval 0.75 to 1.36. The upper end of that interval is the gene's LOEUF score, 1.36, which puts it in group 5 of 6, group 1 being the genes least tolerant of losing a copy. Missense variants: 334 observed, 386.08 expected, observed/expected ratio (o/e) 0.87, 90% interval 0.79 to 0.95. Synonymous variants: 102 observed, 126.82 expected, observed/expected ratio (o/e) 0.8, 90% interval 0.68 to 0.95.
Homologues: Orthologues: chimpanzee RRH (100% identical), macaque RRH (98% identical), rabbit RRH (90% identical), pig RRH (89% identical), guinea pig RRH (85% identical), mouse Rrh (79% identical), rat Rrh (78% identical), tropical clawed frog rrh (71% identical), zebrafish rrh (69% identical), dog RRH (69% identical), Caenorhabditis elegans nmur-3 (23% identical), Caenorhabditis elegans sro-1 (18% identical). Paralogues in human: OPN4 (28% identical), OPN3 (27% identical), OPN5 (26% identical), OPN1LW (25% identical), OPN1MW (25% identical), OPN1MW2 (25% identical), OPN1MW3 (25% identical), RHO (25% identical), OPN1SW (21% identical).
Diseases named in the same sentence as RRH in open-access papers:
RRH is named in the same sentence as 5 diseases in open-access papers, as found by Europe PMC text mining. Sharing a sentence is not in itself a finding about the gene and the disease. The quoted sentences say what the papers report.
atherosclerosis (1 paper, 2023). A disease characterized by the build-up of fatty material and calcium deposition in the arterial wall resulting in partial or complete occlusion of the arterial lumen. "At the same time, KEGG enrichment analysis revealed the potential signaling pathways of RRH in the treatment of chronic hepatitis, including Hepatitis B (hsa05161), Hepatitis C (hsa05160), Chemical carcinogenesis-receptor activation (hsa05207), Lipid and atherosclerosis signaling pathway (hsa05417)." (PMID 38050220, 2023).
RRH also shares sentences with these, for which no sentence is quoted: chronic hepatitis (1 paper); Hepatitis (1); Hepatitis B (1); Hepatitis C (1).